PGAP6 (post-GPI attachment to proteins 6)
Description:
Involved in the lipid remodeling steps of GPI-anchor maturation. Lipid remodeling steps consist in the generation of 2 saturated fatty chains at the sn-2 position of GPI-anchor proteins (GPI-AP). Has phospholipase A2 activity that removes an acyl-chain at the sn-2 position of GPI-anchors during the remodeling of GPI. Required for the shedding of the GPI-AP CRIPTO, but not CFC1, at the cell surface. Shedding of CRIPTO modulates Nodal signaling by allowing soluble CRIPTO to act as a Nodal coreceptor on other cells. Also indirectly involved in the translocation of RAC1 from the cytosol to the plasma membrane by maintaining the steady state amount of CAV1-enriched plasma membrane subdomains, stabilizing RAC1 at the plasma membrane. In contrast to myomaker (TMEM8C), has no fusogenic activity.
Synonyms: GPI-PLA2; TMEM6; TMEM8; TMEM8A; M83
Tractability: Antibody: UniProt places it where antibodies can reach, with high confidence; UniProt predicts a signal peptide or a membrane-spanning region; its Gene Ontology location is reachable by antibodies, with medium confidence. PROTAC: ubiquitination databases record sites on it.
Gene: Protein-coding gene on chromosome 16 (370,788 to 387,113, reverse strand). Ensembl gene ENSG00000129925.
Subcellular location: Cell membrane; Lysosome membrane
Subcellular location (Human Protein Atlas): Nucleoplasm; Cytokinetic bridge
Gene Ontology:
Molecular function: protein binding; phospholipase A2 activity
Cellular component: extracellular exosome; lysosomal membrane; nucleoplasm; plasma membrane; membrane
Genetic constraint (gnomAD): Loss-of-function variants: 61 observed, 63.45 expected, observed/expected ratio (o/e) 0.96, 90% interval 0.78 to 1.19. The synonymous counts are far from expectation, so gnomAD's model fits this gene poorly and the ratio says little. Missense variants: 1,188 observed, 1,027.2 expected, observed/expected ratio (o/e) 1.16, 90% interval 1.1 to 1.21. Synonymous variants: 575 observed, 452.47 expected, observed/expected ratio (o/e) 1.27, 90% interval 1.19 to 1.36.
Homologues: Orthologues: chimpanzee PGAP6 (99% identical), macaque PGAP6 (94% identical), mouse Pgap6 (75% identical), rat Pgap6 (75% identical), dog PGAP6 (75% identical), pig PGAP6 (68% identical), tropical clawed frog pgap6 (50% identical), zebrafish pgap6 (38% identical). Paralogues in human: TMEM8B (41% identical), MYMK (9% identical).
Diseases named in the same sentence as PGAP6 in open-access papers:
PGAP6 is named in the same sentence as 12 diseases in open-access papers, as found by Europe PMC text mining. Sharing a sentence is not in itself a finding about the gene and the disease. The quoted sentences say what the papers report.
dementia (2 papers, 2023). Loss of intellectual abilities interfering with an individual's social and occupational functions. "PGAP6, which encodes post-glycosylphosphatidylinositol attachment to proteins 6, was also found to be differentially expressed with higher expression levels in the MCI group compared to both the CN (P-value = 0.014) and dementia (P-value = 0.045) groups." (PMID 37066364, 2023).
PGAP6 also shares sentences with these, for which no sentence is quoted: synucleinopathies (4 papers); Alzheimer disease (1); Ataxia (1); Hypertension (1); immune dysfunction (1); infection (1); lysosomal storage disorders (1); neurologic disease (1); osteosarcoma (1); tumor (1); α-thalassemia (1).